ARL6IP5 (ARF like GTPase 6 interacting protein 5)
Description:
Regulates intracellular concentrations of taurine and glutamate. Negatively modulates SLC1A1/EAAC1 glutamate transport activity by decreasing its affinity for glutamate in a PKC activity-dependent manner. Plays a role in the retention of SLC1A1/EAAC1 in the endoplasmic reticulum.
Synonyms: DERP11; JWA; PRAF3; HSPC127; GTRAP3-18; Yip6b; addicsin; hp22; jmx
Tractability: Antibody: UniProt places it where antibodies can reach, with medium confidence; UniProt predicts a signal peptide or a membrane-spanning region; its Gene Ontology location is reachable by antibodies, with medium confidence. PROTAC: ubiquitination databases record sites on it; its protein half-life has been measured.
Gene: Protein-coding gene on chromosome 3 (69,084,937 to 69,106,092, forward strand). Ensembl gene ENSG00000144746.
Subcellular location: Endoplasmic reticulum membrane; Cell membrane; Cytoplasm; Cytoplasm, cytoskeleton
Subcellular location (Human Protein Atlas): Endoplasmic reticulum
Pathways (Reactome):
Neuronal System: Glutamate Neurotransmitter Release Cycle
Gene Ontology:
Molecular function: protein binding
Biological process: intrinsic apoptotic signaling pathway in response to oxidative stress; negative regulation of mitochondrial membrane potential; positive regulation of apoptotic process; positive regulation of stress-activated MAPK cascade; protein transport; L-glutamate transmembrane transport; negative regulation of L-glutamate import across plasma membrane; negative regulation of transport
Cellular component: membrane; cytoplasm; endoplasmic reticulum membrane; plasma membrane; cytoskeleton; presynaptic cytosol
Genetic constraint (gnomAD): Loss-of-function variants: 6 observed, 13.83 expected, observed/expected ratio (o/e) 0.43, 90% interval 0.24 to 0.86. The upper end of that interval is the gene's LOEUF score, 0.86, which puts it in group 3 of 6, group 1 being the genes least tolerant of losing a copy. Missense variants: 208 observed, 264.88 expected, observed/expected ratio (o/e) 0.79, 90% interval 0.7 to 0.88. Synonymous variants: 91 observed, 98.5 expected, observed/expected ratio (o/e) 0.92, 90% interval 0.78 to 1.1.
Homologues: Orthologues: chimpanzee ARL6IP5 (100% identical), macaque ARL6IP5 (98% identical), rabbit ARL6IP5 (96% identical), dog ARL6IP5 (95% identical), guinea pig ARL6IP5 (94% identical), pig ARL6IP5 (91% identical), rat Arl6ip5 (91% identical), mouse Arl6ip5 (90% identical), tropical clawed frog arl6ip5 (73% identical), zebrafish arl6ip5a (65% identical), zebrafish arl6ip5b (63% identical), Drosophila melanogaster Jwa (37% identical), and 1 more. Paralogues in human: PRAF2 (43% identical).